IL4 (interleukin 4)
Diseases named in the same sentence as IL4 in open-access papers (continued):
Sharing a sentence is not in itself a finding about the gene and the disease.
ovarian carcinoma (26 papers, 2002 to 2026). A malignant neoplasm originating from the surface ovarian epithelium. "In the tumor microenvironment of ovarian cancer, Apo-A1-induced cholesterol efflux inhibits IFNγ-related gene expression, which in turn enhances IL-4 signaling in tumor-associated macrophages to promote immunosuppression." (PMID 38534755, 2024). "Interleukin‐4 (IL‐4), primarily secreted by ovarian cancer cells, promotes resistance to anti‐PD‐1 immunotherapy by shaping an immunosuppressive tumor microenvironment (TME) through macrophage modulation." (PMID 40968783, 2026). "provide crucial insights into the role of IL-4 in shaping specific macrophage subsets in ovarian cancer." (PMID 40330466, 2025). "M2 macrophages, induced by IL-4, significantly enhance the proliferation, migration, and invasion of ovarian cancer cells while inhibiting their apoptosis in vitro." (PMID 40330466, 2025). "Ovarian cancer cells also secrete interleukin-4 (IL-4), which directs the formation of an immunosuppressive TIME (tumor immune microenvironment)." (PMID 40666944, 2025). "Ovarian cancer cells are known to promote cholesterol efflux in TAM by inducing IL‐4 mediated arginase programming." (PMID 40820860, 2025). "Ovarian cancer cells prompt the release of cholesterol from TAMs, boost IL‐4 signaling, and suppress interferon (IFN)‐γ‐induced gene expression." (PMID 38411356, 2024). "These IL‐4 signaling and cholesterol efflux pathways in TAMs significantly contributed to ovarian cancer progression." (PMID 38411356, 2024). "In this study the expression of the macrophage regulatory gene IL4 in the OV group was significantly down-regulated, suggesting that the prognosis of ovarian cancer was poor." (PMID 39478854, 2024). "There are research reports that IL-4 has anti-tumor effects, and its expression has important reference value for judging the malignancy of ovarian cancer and predicting prognosis." (PMID 39478854, 2024). "In our study, we found that FPR2 played an auxoaction on the secretion of IL-10 and IL-4 in ovarian cancer cells and the induction of M2 macrophage polarization." (PMID 34930387, 2021). "It has been reported that IFN-α and IFN-γ, applied in combination with IL-4 fused to Pseudomonas exotoxin, inhibit tumor growth in an experimental mouse model of human ovarian cancer." (PMID 33266317, 2020). "We have shown that MSCs and MSCs CM induced a significant increase in the level of IL-4 AND IL-10 in the 4 ovarian cancer cell lines." (PMID 31351482, 2019). "In search for a more powerful vaccine, we compared the efficacies of IL-15 DCs and IL-4 DCs in the context of a metastatic murine ovarian cancer model." (PMID 30621204, 2019). "This conclusion is based on a spatial functional genomics screen (Perturb‐map) performed in preclinical ovarian cancer models, which recapitulated tumor heterogeneity and revealed that IL‐4 directs localized TME composition, driving clonal selection and immunotherapy resistance." (PMID 40968783, 2026). "In ovarian cancer, it has shown promise by targeting the tumor microenvironment, specifically by suppressing the polarization of macrophages into the M2 pro-tumor phenotype, a shift usually triggered by interleukin IL-4 and IL-13 exposure." (PMID 40330466, 2025). "Furthermore, IL-4 cytotoxin has shown significant anti-tumor activity against IL4R-expressing ovarian carcinoma in a mouse model of ovarian cancer." (PMID 40656893, 2025). "Significant lower expression of IL-4 in malignant ovarian tissues compared to benign cysts suggests the need for more studies in the future to reveal if this cytokine has an antitumor role in ovarian cancer." (PMID 25999622, 2015). "The study further demonstrated that IL-4 signaling operates within distinct TME neighborhoods, where even a small fraction of IL-4-producing ovarian cancer cells can exert a significant impact on the surrounding immune landscape." (PMID 40330466, 2025).
ovarian carcinoma (continued). "Six out of 20 genes (IFN-γ, Foxp3, IL-4, BCL-2, Oct4 and survivin) selected by the Laplacian score showed key roles in the development of ovarian cancer and their prognostic values were clinically and statistically confirmed." (PMID 34181334, 2021). "The IL-4 signaling pathway, through its receptor IL4R, may be involved in regulating the immunosuppressive microenvironment of ovarian cancer." (PMID 40656893, 2025). "IL-4, IL-10 and TGF-β are also central to macrophage-mediated immunosuppression in ovarian cancer." (PMID 40330466, 2025). "In this study, the expression of IL4 in ovarian cancer tissues was significantly reduced compared with the Nor group, suggesting that the prognosis of ovarian cancer was poor." (PMID 39478854, 2024). "The expression of some immune-related molecules, such as IL-4, IL-6, IL-10, and GM-CSF, were analyzed, but none of them was found to be related to the induction of B7-H4 expression in ovarian cancer cells." (PMID 36609273, 2023). "The cytokines, including IL-4 (p = 0.017) and TNF-α (p = 0.046), significantly decreased while others such as TGF-β (p = 0.013), IL-6 (p = 0.016), and IL-10 (p = 0.018) were elevated in ascites of ovarian cancer patients, when the disease progressed to advanced stages." (PMID 23082146, 2012). "HM-1 and ID8 mouse ovarian cancer cells expressed very low levels of VISTA, and the expression did not increase following treatment with IFN-γ, IL-4, IL-6, IL-10, IL-17, or TNF-α." (PMID 30382166, 2019).
anaphylaxis (25 papers, 2014 to 2026). An acute hypersensitivity reaction that occurs from exposure to an allergen. "IL-4 from these basophils potentiated DC-driven Th2 cell polarization and was essential for the increase in serum IL-4 concentrations and susceptibility to oral anaphylaxis in OVA + SEB-sensitized mice." (PMID 41005294, 2025). "We observed enriched representation of 15 anaphylaxis‐associated pathways and identified 15 genes involved in IgE/FcεRI signaling that were convergently modulated by IFNγ, IL‐33, IL‐4 + IL‐13, and TGFβ." (PMID 40926620, 2025). "Follicular T helper (Tfh) cells, which secrete IL-4, and the Tfh13 subtype, which secretes IL-4, IL-5 and IL-13, are associated with high-affinity IgE, which is involved in anaphylaxis with food allergens." (PMID 39962262, 2025). "T cells were the major source of IL-4 that mediated the heightened susceptibility to anaphylaxis in OVA + SEB-sensitized mice." (PMID 41005294, 2025). "In all, these conditions support that increases in MCs, their mediators, the IL‐4 signaling cascade, and the formation of allergic IgE antibodies collectively promote anaphylaxis." (PMID 41331837, 2026). "The role of Paneth cells and goblet cells in the IL-4-dependent increase in intestinal permeability and exaggeration of oral anaphylaxis needs investigation." (PMID 41005294, 2025). "In this study, the SA group showed allergic responses, such as increased sIgE, sIgG1, histamine, mMCP-1, anaphylaxis score, and IL-4, decreased IFN-γ and body temperature, which were consistent with previous study." (PMID 35804699, 2022). "Upon challenge, enhanced IgE-dependent intestinal mast cell expansion, enhanced concentrations of IL-4 in serum as well as systemic anaphylaxis were monitored." (PMID 33717110, 2021). "IL-4 amplifies IgE- and histamine-induced endothelial dysfunction, fluid extravasation, and the severity of anaphylaxis." (PMID 34575019, 2021). "Collectively, IL-4 amplifies IgE- and histamine-induced VE dysfunction, fluid extravasation, and the severity of anaphylaxis through a VE-IL-4Rα/ABL1-dependent mechanism." (PMID 32789004, 2020). "Recently, our group identified an important role for IL-4 in amplifying histamine-induced anaphylaxis responses." (PMID 32789004, 2020). "Distinct Tfh subsets, characterized by differential production of IL-4 and IL-13, may further determine whether IgE responses remain low-affinity or mature into high-affinity antibodies capable of driving anaphylaxis." (PMID 41917787, 2026). "We next examined whether basophil-derived IL-4 is sufficient to drive the exaggerated passive oral anaphylaxis in mice epicutaneously sensitized to OVA + SEB." (PMID 41005294, 2025). "IL-4 signaling might increase CXCL1 expression to mediate allergic inflammations such as anaphylaxis." (PMID 40005151, 2025). "IL-4 could potentially target intestinal epithelial cells, MCs, and vascular endothelial cells to exaggerate oral anaphylaxis in OVA + SEB-sensitized mice." (PMID 41005294, 2025). "These genes will be helpful for better understanding IL-4-promoted anaphylaxis." (PMID 40005151, 2025). "Thus, basophil-derived IL-4 plays a critical role in the enhanced Th2 polarization, increased serum IL-4 concentrations, and exaggerated oral anaphylaxis in mice epicutaneously sensitized to OVA in the presence of SEB." (PMID 41005294, 2025). "IL-4 is known to induce B cell differentiation, IgE production, and anaphylaxis." (PMID 37569351, 2023). "Higher levels of histamine and IL-4 have been reported in the serum of human patients with severe anaphylaxis, indicating that these molecules may be involved in the expression of the severe disease phenotype." (PMID 34575019, 2021). "In addition, aiTregs reprogrammed by excessive responses to IL-4 aggravate food allergic anaphylaxis through signals from FcεRI expressed on mast cells." (PMID 28234975, 2017).
anaphylaxis (continued). "However, Th2 cytokines such as IL-4, IL-5, and IL-13 are thought to promote allergic reactions including eosinophil infiltration and IgE production, which induce Th2-dependent antibodies and systemic anaphylaxis." (PMID 36499554, 2022). "Key soluble mediators such as histamine and IL-4 were commonly being studied in IgE-mediated anaphylaxis but there is no consensus on the soluble mediators for IgG-mediated anaphylaxis." (PMID 30809224, 2019).
visceral leishmaniasis (25 papers, 2009 to 2025). A severe form of leishmaniasis characterized by irregular bouts of fever, substantial weight loss, swelling of the spleen and liver, and anemia (which may be serious). "Consequently, current research within our team is aimed at unraveling IL-4 and IL-13 signaling on specific target immune cells during visceral leishmaniasis using our cell-type-specific IL-4Rα-deficient mouse models." (PMID 29176972, 2017). "However, IL-4 null mice are more susceptible to visceral leishmaniasis than their wild-type counter parts after drug therapy, suggesting that IL-4 is necessary for effective chemotherapy in visceral leishmaniasis." (PMID 21912560, 2012). "In this context, pretreatment serum levels of interferon-gamma (IFN-γ), tumor necrosis factor-α (TNF-α), IL-4, IL-6, IL-8, IL-10, and IL-27 are elevated in Brazilian individuals with untreated kala-azar." (PMID 41003560, 2025). "In human and murine models of visceral leishmaniasis, IL-4 is hardly detectable in CD4 + and CD8 + lymphocytes, which does not agree with canine findings, at least according to the results of this study." (PMID 36703227, 2023). "Increased levels of IL-4 production by neutrophils stimulated with soluble Leishmania antigens can occur in human visceral leishmaniasis patients." (PMID 31000764, 2019). "In a parallel study, we explored the efficacy of IL-4 as an adjuvant in DC-mediated vaccination as in the context of visceral leishmaniasis, IL-4 mediates protective immunity and has been shown to instruct successful chemotherapy and vaccination responses." (PMID 29176972, 2017). "Therapy with AmB induced elevated production of TNFα, IFNγ and IL-12 in splenocytes of treated mice, and PBMC of kala-azar patients with reduced IL-4, IL-10 and TGFβ production." (PMID 25884796, 2015). "Visceral leishmaniasis cases also exhibited an increase in their anti-inflammatory and regulatory cytokine patterns, as shown by the higher amounts of IL-4, and particularly IL-10 (P <0.0001)." (PMID 24886212, 2014). "Nonetheless, in BALB/c mice vaccinated with recombinant A2 protein or LRP plus saponin, the protection against cutaneous or visceral leishmaniasis have been also correlated with a decrease in Leishmania-specific IL-4 and IL-10 mediated response." (PMID 23573301, 2013). "However, in view of several other reports related to the uncertain status of IL-4 in the context of visceral leishmaniasis, the significance of the Wnt5A-IL-4 connection in our study is unclear at present." (PMID 35197983, 2022). "Overall, the role of IL-4 in canine visceral leishmaniasis remains controversial." (PMID 31000764, 2019). "In experimental visceral leishmaniasis, the role of IL-4 in the susceptibility to visceral disease is not clearly defined." (PMID 30150896, 2018). "It was therefore postulated that other vital genes involved in the IL-4 pathway could provide genetic clues of IL-4 regulation and immunopathogenesis during kala-azar." (PMID 27051668, 2016). "In visceral leishmaniasis both, IL-4 and IL-13 play a positive role in granuloma formation and maturation (also pointing to IL-4Rα-dependent inflammatory cell recruitment as found here for pulmonary cryptococcosis) and are essential for optimal development of IFN-γ responses." (PMID 24475277, 2014). "Thus, our results for TNF- α and IL-4 are in accordance with the literature regarding their role in canine visceral leishmaniasis." (PMID 23668673, 2013). "However, the point that an IL-4-mediated Th2 response renders mice necessarily susceptible has never been proven for visceral leishmaniasis." (PMID 22802978, 2012). "Furthermore, it has been demonstrated that endogenous IL-4 is necessary for effective drug therapy with sodium stibogluconate against visceral leishmaniasis in BALB/c mice, as IL-4-deficient mice responded poorly to this treatment and showed increased parasite burdens in infected tissues." (PMID 22802978, 2012).
visceral leishmaniasis (continued). "In Sudan, individuals with kala-azar have high levels of IFN-γ, TNF-α, IL-4, IL-6, IL-10, IL-12, and IL-17A." (PMID 41003560, 2025). "It has been evidenced that this protein elicits IL-4 and IL-10 expression, and it also suppresses IL-12 and IFN-γ expression in blood-derived monocytes from patients with visceral leishmaniasis." (PMID 35634280, 2022). "Earlier studies in this context revealed that the IFN-γ/IL-4 paradigm of resistance and susceptibility to intracellular infection, as defined for species causing cutaneous leishmaniasis (CL), does not apply holistically to species causing visceral leishmaniasis (VL)." (PMID 31475014, 2019). "In a hamster model of visceral leishmaniasis (VL), Osorio and colleagues showed that Leishmania donovani infected macrophages displayed enhanced STAT6 and STAT3 signalling in response to the growth factors FGF2 and IGF1, further enhanced by co-stimulation with IL-4 or IL-10." (PMID 29352310, 2018). "In addition, IL-4−/− and IL-4Rα−/− BALB/c mice are more susceptible to infection with L. donovani and also experimental visceral leishmaniasis in C57BL/10 mice is independent of IL-4 and the associated Th2 immune response." (PMID 23825956, 2013).
chronic obstructive pulmonary disease (24 papers, 2013 to 2025). A chronic and progressive lung disorder characterized by the loss of elasticity of the bronchial tree and the air sacs, destruction of the air sacs wall, thickening of the bronchial wall, and mucous accumulation in the bronchial tree. "One such disease state is allergic airway inflammation caused by type 2 (T2) cytokines (IL-4, IL-5, IL-13), which is common in both children and adults and has been associated with the development of both asthma and chronic obstructive pulmonary disease (COPD) in a subgroup of patients." (PMID 33046696, 2020). "Azithromycin decreases the secretion of IL-4, IL-5, IL-13, and IL-17A from peripheral blood mononuclear cells in patients with chronic obstructive pulmonary disease (COPD)." (PMID 37357527, 2023). "Pathways including “IL-4 signaling” and “airway pathology in chronic obstructive pulmonary disease” were significantly different between mouse strains." (PMID 33587776, 2021). "IL-4 is also a major player in respiratory pathologies such as chronic obstructive pulmonary disease (COPD) and asthma." (PMID 29748496, 2018). "It has also been found that 45 min of H2 gas inhalation reduced airway and pulmonary inflammation in chronic obstructive pulmonary disease (COPD) and asthma patients by reducing MCP-1, IL-6, and IL-4 levels." (PMID 37509530, 2023). "The authors assessed levels of acetylated histone H4 in the peripheral blood mononuclear cells of Chronic Obstructive Pulmonary Disease (COPD) patients and reported higher acetylation levels in patients with higher IL-8 levels and in patients with lower IL-4 levels." (PMID 31205673, 2019). "The IL-4/IL-13 antagonist, IgG1, and an anti-IgE monoclonal antibody (Omalizumab®) have been administered as dried powder inhaler preparations for asthma, chronic obstructive pulmonary disease (COPD), or other related lung diseases." (PMID 30126135, 2018). "Analysis of primary bronchial epithelial cells (PBECs) from patients with severe chronic obstructive pulmonary disease (COPD) revealed significantly elevated TNF-α and IFN-γ levels, reduced IL-4 and IL-13 levels, and elevated Th1-dominated cytokine responses." (PMID 38495892, 2024).